DNMT3A (DNA methyltransferase 3 alpha)
Description:
Required for genome-wide de novo methylation and is essential for the establishment of DNA methylation patterns during development. DNA methylation is coordinated with methylation of histones. It modifies DNA in a non-processive manner and also methylates non-CpG sites. May preferentially methylate DNA linker between 2 nucleosomal cores and is inhibited by histone H1 (By similarity). Plays a role in paternal and maternal imprinting (By similarity). Required for methylation of most imprinted loci in germ cells (By similarity). Acts as a transcriptional corepressor for ZBTB18 (By similarity). Recruited to trimethylated 'Lys-36' of histone H3 (H3K36me3) sites (By similarity). Can actively repress transcription through the recruitment of HDAC activity (By similarity). Also has weak auto-methylation activity on Cys-710 in absence of DNA (By similarity).
Synonyms: M.HsaIIIA; DNMT3A2; HESJAS; TBRS
Tractability: Small molecule: an approved drug acts on it; a structure with a bound ligand is known; a high-quality ligand is known; it belongs to a druggable protein family. PROTAC: UniProt records ubiquitination sites on it; ubiquitination databases record sites on it; its protein half-life has been measured; a small molecule that binds it is known.
Target class: Reader; Methyl-lysine/arginine binding protein; Epigenetic regulator; PWWP domain
Gene: Protein-coding gene on chromosome 2 (25,227,855 to 25,342,590, reverse strand). Ensembl gene ENSG00000119772.
Subcellular location: Nucleus; Chromosome; Cytoplasm
Subcellular location (Human Protein Atlas): Nucleoplasm; Vesicles
Pathways (Reactome):
Gene expression (Transcription): DNA methylation; PRC2 methylates histones and DNA; Regulation of endogenous retroelements by Piwi-interacting RNAs (piRNAs)
Chromatin organization: RMTs methylate histone arginines
Disease: Defective pyroptosis
Metabolism of proteins: SUMOylation of DNA methylation proteins
Gene Ontology:
Molecular function: DNA (cytosine-5-)-methyltransferase activity; DNA binding; identical protein binding; lncRNA binding; protein binding; RNA polymerase II cis-regulatory region sequence-specific DNA binding; RNA polymerase II-specific DNA-binding transcription factor binding; unmethylated CpG binding; protein-cysteine methyltransferase activity; transcription corepressor activity; chromatin binding; methyltransferase activity
Biological process: DNA methylation-dependent constitutive heterochromatin formation; negative regulation of gene expression via chromosomal CpG island methylation; negative regulation of transcription by RNA polymerase II; regulatory ncRNA-mediated heterochromatin formation; negative regulation of DNA-templated transcription; cellular response to ethanol; cellular response to hypoxia; hepatocyte apoptotic process; neuron differentiation; positive regulation of cellular response to hypoxia; regulation of gene expression; response to cocaine; response to estradiol; response to ethanol; response to ionizing radiation; response to lead ion; response to nutrient levels; response to toxic substance; response to vitamin A; response to xenobiotic stimulus; transposable element silencing by piRNA-mediated DNA methylation
Cellular component: catalytic complex; chromosome; cytoplasm; euchromatin; nuclear matrix; nucleoplasm; nucleus; chromosome, centromeric region; heterochromatin; XY body
Genetic constraint (gnomAD): Loss-of-function variants: 267 observed, 106.98 expected, observed/expected ratio (o/e) 2.5. Missense variants: 1,029 observed, 1,220 expected, observed/expected ratio (o/e) 0.84, 90% interval 0.8 to 0.89. Synonymous variants: 432 observed, 479.44 expected, observed/expected ratio (o/e) 0.9, 90% interval 0.83 to 0.98.
Gene-disease validity (ClinGen):
ClinGen rates the evidence that DNMT3A causes each of these diseases.
Tatton-Brown-Rahman overgrowth syndrome (autosomal dominant): Definitive. A rare multiple congenital anomalies syndrome characterized by greater height, mild to moderate intellectual disability and distinctive facial appearance like round face, heavy, horizontal eyebrows and narrow palpebral fissures.
Heyn-Sproul-Jackson syndrome (autosomal dominant): Limited.
Cancer hallmarks: escaping programmed cell death (promotes); change of cellular energetics (promotes); proliferative signalling (promotes); escaping programmed cell death (suppresses); escaping immune response to cancer (promotes); invasion and metastasis (promotes); angiogenesis (suppresses)
Homologues: Orthologues: chimpanzee DNMT3A (99% identical), macaque DNMT3A (99% identical), dog DNMT3A (98% identical), pig DNMT3A (97% identical), guinea pig DNMT3A (96% identical), mouse Dnmt3a (96% identical), rat Dnmt3a (96% identical), rabbit DNMT3A (87% identical), tropical clawed frog dnmt3a (79% identical), zebrafish dnmt3ab (72% identical), zebrafish dnmt3aa (62% identical). Paralogues in human: DNMT3B (47% identical), DNMT3L (17% identical), PWWP2A (13% identical), PWWP2B (10% identical).
Diseases named in the same sentence as DNMT3A in open-access papers:
DNMT3A is named in the same sentence as 431 diseases in open-access papers, as found by Europe PMC text mining. Sharing a sentence is not in itself a finding about the gene and the disease. The quoted sentences say what the papers report.
acute myeloid leukemia (250 papers, 2006 to 2026). Acute myeloid leukemia (AML) is a group of neoplasms arising from precursor cells committed to the myeloid cell-line differentiation. "Somatic mutations in the de novo DNA methyltransferase DNMT3A occur in approximately one-third of cytogenetically normal acute myeloid leukemia (AML)." (PMID 39580581, 2025). "Mutations in the DNMT3A gene can lead to developmental disorders, such as Tatton–Brown–Rahman syndrome, and are also associated with certain cancers, including acute myeloid leukemia." (PMID 39996888, 2025). "For instance, mutations in DNMT3A (a DNA methyltransferase) have been linked to the development of acute myeloid leukaemia (AML), highlighting the role of DNA methylation in cellular plasticity." (PMID 39316249, 2025). "Clinical trials have confirmed the effectiveness of Daunorubicin in treating acute myeloid leukemia with the DNMT3A (p.V687F) mutation, and professional guidelines have endorsed its use." (PMID 38672648, 2024). "DNMT3A somatic mutations are frequent in myeloid neoplasms such as acute myeloid leukemia and MDS, and they are observed at unusually high frequency in VEXAS." (PMID 37586319, 2023). "To refine the biological and prognostic significance of DNMT3A mutations in acute myeloid leukemia (AML), we assessed the impact of DNMT3A variant allele frequency (VAF) and its comutations in this study." (PMID 36912186, 2023). "Somatic mutations of the DNMT3A gene were correlated with lower overall survival in patients with acute myeloid leukemia, and dysregulation of the DNMTs in leukemia can contribute to disease progression by silencing tumor suppressor genes." (PMID 37998740, 2023). "DNMT3A mutations are common in hematological malignancies such as acute myeloid leukemia and myelodysplastic syndromes." (PMID 37998740, 2023). "Mutations in DNMT3A have been found in several types of cancer, including acute myeloid leukaemia, myelodysplastic syndromes, and other haematological malignancies." (PMID 37175518, 2023). "Loss-of-function mutations in the DNA methyltransferase 3A (DNMT3A) are seen in a large number of patients with acute myeloid leukemia (AML) with normal cytogenetics and are frequently associated with poor prognosis." (PMID 36976647, 2023). "DNMT3A mutations are relatively common in patients with cytogenetically normal acute myeloid leukemia (AML) and myelodysplastic syndrome (MDS), accounting for a quarter of AML cases." (PMID 36835136, 2023). "Clonal hematopoiesis is caused most frequently by somatic mutations in DNMT3A, which are also a common feature of normal karyotype acute myeloid leukemia (AML)." (PMID 37160317, 2023). "Preleukemic cell detection, particularly in acute myeloid leukemia patients with mutant DNMT3A and TET2 genes, has been linked to leukemia genesis." (PMID 37047003, 2023). "Most studies have sought to characterise their distinct roles through knockdown or inactivation, and from the study of diseases such as acute myeloid leukaemia in which DNMT3A is frequently mutated." (PMID 35987848, 2022). "For example, hematological diseases like acute myeloid leukemia (AML) have mutations in the DNMT3A gene, whereas inactivating mutations in DNMT1 are related to genome-wide alterations of DNA methylation in colon cancer." (PMID 36012258, 2022). "Meanwhile, in acute myeloid leukemia, the ectopic expression of miR-29b caused a reduced expression of DNMT3A and DNMT3B at both RNA and protein levels." (PMID 36012258, 2022). "Mutations within the DNMT3A gene are common in acute myeloid leukaemia and are associated with global loss of methylation." (PMID 35987848, 2022). "DNA methyltransferase 3A (DNMT3A) often mutate on arginine 882 (DNMT3AR882) in acute myeloid leukemia (AML)." (PMID 36303144, 2022). "DNA methyltransferase 3 A (DNMT3A) is the most frequently mutated gene in acute myeloid leukemia (AML)." (PMID 36163326, 2022).
acute myeloid leukemia (continued). "Previous studies suggested that DNMT3A mutations lead to chemotherapy resistance in acute myeloid leukemia." (PMID 34663800, 2021). "Mutations in the multifunctional ribonucleoprotein NPM1 are identified as drivers for acute myeloid leukemia in 30% of patients and frequently co-occur with pre-leukemic DNMT3A mutations." (PMID 33649320, 2021). "Nine months after first admission the patient developed acute myeloid leukemia with DNMT3a and TET2 mutations." (PMID 33708776, 2021). "DNMT3A mutations are frequently identified in acute myeloid leukemia (AML) and indicate poor prognosis." (PMID 34067359, 2021). "DNA (cytosine-5)-methyltransferase 3A (DNMT3A) mutations occur in ~20% of de novo acute myeloid leukemia (AML) patients, and >50% of these mutations in AML samples are heterozygous missense alterations within the methyltransferase domain at residue R882." (PMID 34663800, 2021). "An increased methylation of DNMT3A target genes, compatible with a gain-of-function effect of the alteration, was observed in saliva DNA from the proband and in one independent acute myeloid leukemia sample carrying the same p.Gly332Arg variant." (PMID 33182397, 2020). "For instance, mutations in DNA methylation enzyme DNMT3a are found in ~22% of patients with acute myeloid leukemia (AML) and T cell lymphoma have been associated with poor disease outcomes." (PMID 32760400, 2020). "Approximately 22% of cytogenetically normal acute myeloid leukemia (CN-AML) patients carry a DNMT3A mutation, from which about 60% are localized in the catalytic domain, at the R882 hotspot." (PMID 32457355, 2020). "DNMT3A mutations occur in about one fifth of acute myeloid leukemia (AML) cases, and these mutations are associated with reduced enzymatic activity and genomic methylation in the leukemia cells." (PMID 32751889, 2020). "TET2 and DNMT3A mutations were first described in myeloid neoplasms, such as acute myeloid leukemia (AML), myelodysplastic syndrome or chronic myelomonocytic leukemia (CMML), with CMML carrying the highest frequency of TET2 mutations." (PMID 32796826, 2020). "This is of particular importance as mutations in DNMT3a are associated with poor outcomes in myelodysplastic syndrome and acute myeloid leukemia patients, indicating a potential risk of tumorigenesis if DNMT3a is targeted by epigenetic drugs." (PMID 31306451, 2019). "Extensive studies of the role of DNMT3A in hematopoietic stem cell (HSC) differentiation are also reported, including the regular occurrence of somatic DNMT3A variants in patients with acute myeloid leukemia (AML)." (PMID 31160375, 2019). "Mutation R882H in DNA methyltransferase 3A (DNMT3A) was frequently found in hematological cancer, and up to 60% of patients with acute myeloid leukemia (AML) carry this mutation in heterozygous." (PMID 31013831, 2019). "DNMT3A R882H, a frequent mutation in acute myeloid leukemia (AML), plays a critical role in malignant hematopoiesis." (PMID 31703632, 2019). "The TBRS variant, Arg882His, which is also the most prominent somatic variant of DNMT3A in acute myeloid leukemia (AML) patients, has been extensively studied." (PMID 31091831, 2019). "Genes associated with the pathogenesis of acute myeloid leukemia, such as DNMT3A, NRAS, RUNX1, EZH2, and KRAS, were more commonly mutated in the hypermethylation group." (PMID 30635552, 2019). "We studied the combined effect of both Ptpn11 gain-of-function mutation (D61Y) and Dnmt3a haploinsufficiency on mouse hematopoiesis, the presence of which has been described in both juvenile myelomonocytic leukemia and acute myeloid leukemia patients." (PMID 29464054, 2018). "Particularly interesting was the finding of the heterozygous R882H mutation affecting DNMT3A, which is a mutational hotspot in acute myeloid leukemia (AML) and early T-cell precursor (ETP) adult T-ALL, but is rarely encountered in pediatric T-ALL." (PMID 30304769, 2018).
acute myeloid leukemia (continued). "PTPN11 gain-of-function mutation is the most common mutation found in patients with juvenile myelomonocytic leukemia and DNMT3A loss occurs in over 20% of acute myeloid leukemia patients." (PMID 29464054, 2018). "DNMT3A gene mutation has been associated with poor prognosis in acute myeloid leukemia, but its clinical implications in myelodysplastic syndrome (MDS) and dynamic changes during disease progression remain controversial." (PMID 29619119, 2018). "In acute myeloid leukemia the rate of DNMT3A mutations is even higher and is detected in up to 20% of patients." (PMID 30501028, 2018). "For instance, DNMT3A mutations are associated with a specific DNA hypomethylation pattern in acute myeloid leukemia, and loss of DNMT3A leads to hypomethylation of hematopoietic enhancers in FLT3-ITD–associated leukemias." (PMID 29326230, 2018). "Mutations in DNMT3A have been reported in various hematologic malignancies, including acute myeloid leukemia (AML), myelodysplastic syndrome (MDS) and T-cell lymphoma and leukemia, underlining a potent tumor suppressor role." (PMID 29721185, 2018). "DNMT3A is commonly mutated in myeloid diseases, with mutations found in over 20% of all acute myeloid leukemia (AML) patients, in 8% of myelodysplastic syndrome (MDS) patients, and in smaller frequencies in other leukemias." (PMID 29464054, 2018). "In fact, a loss-of-function mutation of Dnmt3a is one of the earliest mutations that occurs in human acute myeloid leukemia." (PMID 28425913, 2017). "Although these evidences clearly assigned an oncogenic role to DNMT3A in tumorigenesis, the recently discovered DNMT3A mutations in acute myeloid leukemia (AML) suggested that its role in cancer is more complex than previously thought." (PMID 28423585, 2017). "Heterozygous somatic mutations in DNMT3A are present in ~15% of cases of acute myeloid leukemia (AML; OMIM 601626) and in a smaller percentage of cases of myelodysplastic syndrome." (PMID 28503201, 2017). "DNA methyltransferase 3A (DNMT3A) mutations occurred in 18%~23% of acute myeloid leukemia (AML) patients, and were considered to be an adverse prognostic factor for adult de novo AML cases." (PMID 28418922, 2017). "Recently, Dnmt3a has attracted much attention, as it is one of the most frequently mutated genes in cancer, especially in acute myeloid leukemia." (PMID 28425913, 2017). "Aberrant DNMT3A methylation was also observed in other cancers, such as in acute myeloid leukemia and in breast cancer, where DNMT3A expression is associated with advanced stages." (PMID 27999265, 2016). "In the case of DNMT3A, the dominant part of mutations come from various hematopoietic cancers, such as acute myeloid leukemia (AML), chronic myeloid leukemia (CML) or lymphoma." (PMID 27150584, 2016). "The driver classification of DNMT3A by our OG predictor can be attributed to the occurrence of a mutation hot spot in acute myeloid leukemia." (PMID 26110843, 2015). "Somatic mutations in the DNA nucleotide methyltransferase 3A gene (DNMT3A) have been reported approximately in 22 % of de novo acute myeloid leukemia (AML) and 36 % of cytogenetically normal AML." (PMID 25994761, 2015). "The classification of DNMT3A as OG driver can be attributed to the identification of a mutation hot spot on position 882 in acute myeloid leukemia." (PMID 26110843, 2015). "DNMT3A somatic mutations were first discovered by Yamashita and colleagues following sequencing of tissue from adult patients with de novo acute myeloid leukemia (AML)." (PMID 24622842, 2014). "DNA methyltransferase 3A (DNMT3A) mutations were considered to be independently associated with unfavorable prognosis in adults with de novo acute myeloid leukemia (AML), however, there are still debates on this topic." (PMID 24936645, 2014).